SNRPA1 (small nuclear ribonucleoprotein polypeptide A')
Description:
Involved in pre-mRNA splicing as component of the spliceosome. Associated with sn-RNP U2, where it contributes to the binding of stem loop IV of U2 snRNA.
Synonyms: Lea1; U2A'
Tractability: Small molecule: a structure with a bound ligand is known. PROTAC: UniProt records ubiquitination sites on it; ubiquitination databases record sites on it; its protein half-life has been measured.
Gene: Protein-coding gene on chromosome 15 (101,281,510 to 101,295,282, reverse strand). Ensembl gene ENSG00000131876.
Subcellular location: Nucleus
Subcellular location (Human Protein Atlas): Nucleoplasm; Nuclear bodies; Nuclear speckles
Pathways (Reactome):
Metabolism of RNA: mRNA Polyadenylation; mRNA Splicing - Major Pathway
Chromatin organization: CHD1 and CHD2 subfamily
Disease: Dengue Virus-Host Interactions
Immune System: Gene and protein expression by JAK-STAT signaling after Interleukin-12 stimulation
Gene Ontology:
Molecular function: protein binding; RNA binding; U2 snRNA binding
Biological process: mRNA splicing, via spliceosome; spermatogenesis; RNA splicing; spliceosomal snRNP assembly; U2-type prespliceosome assembly
Cellular component: catalytic step 2 spliceosome; nuclear body; nuclear speck; nucleoplasm; nucleus; post-mRNA release spliceosomal complex; post-spliceosomal complex; precatalytic spliceosome; spliceosomal complex; U2-type catalytic step 1 spliceosome; U2-type catalytic step 2 spliceosome; U2-type precatalytic spliceosome; U2-type spliceosomal complex; small nuclear ribonucleoprotein complex; U2 snRNP
Genetic constraint (gnomAD): Loss-of-function variants: 2 observed, 10.39 expected, observed/expected ratio (o/e) 0.19, 90% interval 0.078 to 0.61. The upper end of that interval is the gene's LOEUF score, 0.61, which puts it in group 2 of 6, group 1 being the genes least tolerant of losing a copy. Missense variants: 86 observed, 116.17 expected, observed/expected ratio (o/e) 0.74, 90% interval 0.62 to 0.89. Synonymous variants: 45 observed, 44.19 expected, observed/expected ratio (o/e) 1.02, 90% interval 0.8 to 1.31.
Homologues: Orthologues: chimpanzee SNRPA1 (100% identical), dog SNRPA1 (100% identical), guinea pig SNRPA1 (100% identical), mouse Snrpa1 (98% identical), pig SNRPA1 (94% identical), macaque SNRPA1 (91% identical), rat Snrpa1 (90% identical), zebrafish snrpa1 (81% identical), Drosophila melanogaster U2A (53% identical), Caenorhabditis elegans mog-2 (47% identical). Paralogues in human: LRMDA (26% identical), LRRC72 (20% identical).
Diseases named in the same sentence as SNRPA1 in open-access papers:
SNRPA1 is named in the same sentence as 20 diseases in open-access papers, as found by Europe PMC text mining. Sharing a sentence is not in itself a finding about the gene and the disease. The quoted sentences say what the papers report.
breast cancer (6 papers, 2022 to 2024). A primary or metastatic malignant neoplasm involving the breast. "We also revealed that SNRPA1 deletion notably inhibited the cell proliferation, migration, and invasion both in A549 and H1299 cells; these results are consistent with the findings in ccRCC and breast cancer." (PMID 37277111, 2023). "Also, in breast cancer, SNRPA1 has been shown to alter the splicing of PLEC leading to enhanced lung colonization and cancer cell invasion." (PMID 37457440, 2023). "While some of these spliceosome genes, such as SNRPA1, SNRPD1, USP39, HNRNPU, and HNRNPC, have been shown to play an important role in promoting TNBC cell survival, proliferation, and response to chemotherapy, others are yet to be studied in breast cancer." (PMID 39418101, 2024).
colorectal cancer (6 papers, 2020 to 2023). A primary or metastatic malignant neoplasm that affects the colon or rectum. "Among the prognostic risk factors, SNRPA1 was reported to be highly expressed in colorectal cancer tissues and promoted cancer progression through the regulation of PIK3R1, VEGFC, MKI67, and CDK1." (PMID 36212157, 2022). "For genes associated with RFS, SNRPA1 is an oncogene in colorectal cancer." (PMID 33344083, 2020). "In colorectal cancer (CRC) cells, SNRPA1 binds directly to the BCL-2-associated athanogene-1 (BAG-1) mRNA to decrease the expression of its outcome." (PMID 35281041, 2022).
prostate carcinoma (5 papers, 2017 to 2023). A carcinoma that arises from epithelial cells of the prostate gland. "The gene SNRPA1, a spliceosome component responsible for processing pre-mRNA into mRNA, showed strong prognostic potential in prostate cancer, HCC, and ccRCC." (PMID 36497462, 2022). "In summary, our findings evidenced a relationship between RNA-binding proteins and prostate cancer and indicated the prognostic significance of SNRPA1 in prostate cancer." (PMID 33460399, 2021). "The SNCA, USP20, and SNRPA1 genes were selected for prostate cancer with the accuracy of 73.33 and precision of 66.67." (PMID 29563929, 2017). "Additionally, the results of molecular experiments revealed the proliferative role of SNRPA1 in prostate cancer cells." (PMID 33460399, 2021). "SNRPA1 expression was positively correlated with Gleason score and pathological TNM stage in prostate cancer patients." (PMID 33460399, 2021).
hepatocellular carcinoma (3 papers, 2021 to 2025). A malignant tumor that arises from hepatocytes. "For example, the mTOR pathway is able to participate in the malignant progression of hepatocellular carcinomas by activating SNRPA1." (PMID 34283076, 2021). "Similarly, SNRPA1 was highly expressed in hepatocellular carcinoma and correlated with the clinical stage and OS in hepatocellular carcinoma patients." (PMID 33460399, 2021).
colon cancer (1 paper, 2022). "Our findings indicated that DEDD2, GTF2H5, SNRPA1, BICD1, CELF1, and CLK3 were prognostic risk factors for colon cancer, while ADAD1, CMTR1, HNRNPUL1, FTSJ3, WDR43, THUMPD3, SNRPF were prognostic protective factors." (PMID 36212157, 2022).
liver cancer (1 paper, 2025). An epithelial or non-epithelial malignant neoplasm that arises from the liver. "While prior studies have implicated SNRPA1 and LSM4 in RNA splicing and cancer, and TMED10 in autophagy and vesicle trafficking in melanoma and liver cancer, their involvement in OC has been explored systematically by a limited number of studies." (PMID 40826138, 2025). "This contrasts with prior reports linking SNRPA1 and LSM4 expression to poor prognosis in colorectal and liver cancers, highlighting possible tissue-specific roles or the influence of other clinical and molecular confounders in OC." (PMID 40826138, 2025).
lung adenocarcinoma (1 paper, 2023). A carcinoma that arises from the lung and is characterized by the presence of malignant glandular epithelial cells. "Although a comprehensive comparison of gene expression profiling between lung adenocarcinoma tissues and normal samples identified eight immune‐related genes RBPs for prognostic and efficacious prediction of LUAD patients, SNRPA1 was not included." (PMID 37277111, 2023).
pancreatic cancer (1 paper, 2021). "In cancer research, SNRPA1 bound to the insertion allele of rs386772267 related to pancreatic cancer and influenced gene expression associated with RNA processing and decay." (PMID 33460399, 2021).
tumor (11 papers, 2007 to 2025). "SNRPA1 level, patient age, tumor stage, and tumor grade were all the prognostic factors for ccRCC patients, and SNRPA1 still acted as the independent prognostic risk factor after adjusting for clinical features (p < 0.001)." (PMID 35281041, 2022). "In all, SNRPA1 may prove to be a new biomarker for prognostic prediction, effect tumor immunity, and drug susceptibility in ccRCC." (PMID 35281041, 2022). "Further, SNRPA1 mRNA and protein levels are notably increased in tumor tissues compared with adjacent normal tissues." (PMID 37277111, 2023). "The FFPE slides from ccRCC patients were also employed to verify the elevated SNRPA1 protein level in ccRCC by IHC staining; we observed that tumor slides contained the higher level of SNRPA1 H-score (p <0.01)." (PMID 35281041, 2022). "Multi-databases were collected to evaluate the different expression, prognostic value, DNA methylation, tumor immune microenvironment, and drug sensitivity of SNRPA1 on ccRCC." (PMID 35281041, 2022). "SNRPA1 acted as the risk factor to OS in 12 tumor types, to PFI in 9 tumor types, to DSS in 11 tumor types, and to DFI in 4 types." (PMID 35281041, 2022). "In this study, SNRPA1 was found to be upregulated in ccRCC tissues and was correlated with the migration and invasion of tumor cells." (PMID 35281041, 2022). "Further analysis of the SNRPA1 association to clinical features revealed that patients with a high level of SNRPA1 met more death and mostly in advanced tumor stages." (PMID 35281041, 2022). "To reveal the clinical relevance of SNRPA1, we first compared its mRNA expression levels in tumor and normal samples." (PMID 33460399, 2021). "Consistent with the results from other datasets, the expression of SNRPA1 at protein level was significantly higher in the tumor group compared to that of the normal group." (PMID 33460399, 2021). "A recently discovered structural splicing enhancer (SSE) promotes tumor cell invasion and metastasis by interacting with small nuclear ribonucleoprotein polypeptide A’ (SNRPA1)." (PMID 34484216, 2021). "Finally, the influence of SNRPA1 on LUAD immune microenvironment were validated from the Tumor Immune Estimation Resource database." (PMID 37277111, 2023). "As for the human samples, we collected the fresh tissues of ccRCC and adjacent normal renal tissues and validated the SNRPA1 in mRNA and protein levels; SNRPA1 mRNA and protein levels are significantly increased in tumor tissues as compared with adjacent normal tissues (p < 0.001)." (PMID 35281041, 2022). "All those results indicated that SNRPA1 could regulate immune cell infiltration via different mechanisms under various tumor microenvironments, and further experiment needs to decipher the heterogeneous mechanisms." (PMID 35281041, 2022). "Since there are few studies of SNRPA1 in cancers, especially in tumor immunity, herein we performed a comprehensive analysis of correlation analysis of SNRPA1 expression and immune-regulated genes, immune checkpoint inhibitor genes, and immune cell infiltration degree in pan-cancer levels." (PMID 35281041, 2022). "To explore the biological function of SNRPA1 in different cancer types, we firstly utilized the GSVA to calculate the enrichment scores of 50 canonical tumor associated pathways in pan-cancer level; then the correlation of those enrichment scores and SNRPA1 expression was estimated." (PMID 35281041, 2022). "SNRPA1 inhibition also decreased tumor cell migration and colony formation." (PMID 33460399, 2021). "Interestingly, SNRPA1 could regulate the infiltration of most immune cell types in BRCA, LIHC, LUAD, THCA, and THYM, which indicated that SNRPA1 could be treated as a promising target to regulate tumor immunity in those cancer types." (PMID 35281041, 2022). "For instance, miR-3174 (targeting SNRPA1 mRNA) exhibits oncogenic activity, whereas miR-34a-5p and hsa-miR-644a (targeting SLC2A3 and C8orf37 mRNAs, respectively) possess tumor-suppressive properties." (PMID 36497462, 2022).
tumor (continued). "The strong positive correlation of SNRPA1, TMED10, and PROM2 with suppressive immune regulators like IDO1 and VTCN1, and negative correlation with Th1 and MAIT cell infiltration, suggest that these genes may contribute to an immune-evasive tumor microenvironment." (PMID 40826138, 2025). "For instance, SNRPA1 and TMED10 expression showed consistent negative correlations with Th1 cells and MAIT cells indicating that their overexpression may hinder immune cell recruitment or function within the tumor microenvironment." (PMID 40826138, 2025).
cancer (9 papers, 2008 to 2025). A tumor composed of atypical neoplastic, often pleomorphic cells that invade other tissues. "SNRPA1, a subunit of spliceosome complex, has been implicated in diverse cancers, while its biological effect in LUAD remains elusive." (PMID 37277111, 2023). "Immune checkpoints are important key components for the clinical immunotherapy for tumors; we evaluated the association between SNRPA1 and 47 immune checkpoints in pan-cancer." (PMID 35281041, 2022). "As small nuclear ribonucleoprotein polypeptide A, SNRPA1 was differentially expressed in most cancer types." (PMID 37277111, 2023). "They discovered that elevated SNRPA1 contributed to cell invasion and cancer metastasis; blockage of SNRPA1 is a promising synergistic antitumor strategy for sunitinib sensitivity and anti‐PD‐1 immunotherapy." (PMID 37277111, 2023). "As a crucial component of U2 snRNP, SNRPA1 has been reported as the prognostic biomarker for diverse types of cancers, but still lack the report in ccRCC." (PMID 35281041, 2022). "Among all the cancer types, SNRPA1 expression is correlated with the prognosis of ccRCC patients in OS, PFI, DSS, and DFI." (PMID 35281041, 2022). "As a crucial component of U2 snRNP, small nuclear ribonucleoprotein polypeptide A (SNRPA1) is a potential biomarker for the prognosis of various cancers." (PMID 35281041, 2022). "SNRPA1 may significantly influence the prognosis of multiple cancer types, especially in ccRCC patients." (PMID 35281041, 2022). "The results showed that the expression level of SNRPA1 was significantly different in different stages of various cancer types, suggesting that SNRPA1 may play an important role in progression of various carcinomas." (PMID 35281041, 2022). "The results indicated that SNRPA1 was differentially expressed in most cancer types." (PMID 35281041, 2022). "In addition, SNRPA1 expression was positively correlated with immune inhibitory and stimulatory genes in several cancer types UVM, LIHC, PAAD, KICH, OV, KIPAN, and KIRC, but negatively related in THYM, TGCT, THCA, LUSC, ESCA, CESC, and STES." (PMID 35281041, 2022). "Furthermore, the expression profile of SNRPA1 was validated using the Oncomine, Human Protein Atlas, and Cancer Cell Line Encyclopedia databases." (PMID 33460399, 2021). "In addition, we explored the role of SNRPA1 in pan-cancer level." (PMID 35281041, 2022). "Small nuclear ribonucleoprotein polypeptide A (SNRPA1), a spliceosome component responsible for the splicing reactions of precursor messenger RNAs (pre‐mRNAs), is upregulated in various cancers." (PMID 37277111, 2023). "The results indicated that SNRPA1 mainly positively regulated Myc, MTORC1, G2M checkpoint, E2F target, and DNA repair in most cancer types." (PMID 35281041, 2022). "Moreover, SNRPA1 was related to Myc, MTORC, G2M, E2F, and DNA repair pathways in various cancer types." (PMID 35281041, 2022).
SNRPA1 also shares sentences with these, for which no sentence is quoted: lung carcinoma (2 papers); cardiovascular disorder (1); clear cell renal cell carcinoma (1); COVID-19 (1); glioma (1); immune dysfunction (1); infection (1); melanoma (1); Renal Cell Cancer (1); serous ovarian cancer (1).